TYROBP (transmembrane immune signaling adaptor TYROBP)
Diseases named in the same sentence as TYROBP in open-access papers (continued):
Sharing a sentence is not in itself a finding about the gene and the disease.
kidney cancer (1 paper, 2020). Primary or metastatic malignant neoplasm involving the kidney. "Literature review showed a computational approach named correlation-based feature subset (CFS) identified TYROBP as part of the hub genes in kidney cancer samples using protein-protein interaction network." (PMID 32322218, 2020).
kidney neoplasm (1 paper, 2022). A benign or malignant neoplasm affecting the kidney. "The interaction between TYROBP, SOX6, and kidney neoplasms was drawn, and the inference score of TYROBP and SOX6 on the kidney neoplasms was high." (PMID 36595751, 2022).
liver cirrhosis (1 paper, 2022). "When compared to healthy controls, only 7 DEGs, including 6 up-DEGs (TYMP, TYROBP, TGFBI, LILRA2, GNLY, and GZMB) and 1 down-DEG (CD14) were common to CHB, liver cirrhosis, and HCC." (PMID 35265561, 2022).
lung injury (1 paper, 2025). "Although the relationship between TYROBP and ferroptosis has not yet been fully elucidated, a mouse model of lipopolysaccharide-induced acute lung injury revealed that TREM2 can inhibit DAP12 expression and reduce ferritin accumulation, thereby inhibiting macrophage ferroptosis." (PMID 40895546, 2025).
metastatic cancer (1 paper, 2019). A carcinoma which has spread from the original site of growth to another anatomic site. "The intensity of TYROBP expression was also increased in CTCs compared to normal PBMCs and MCF7 cells, implying an upregulation of this protein in aggressive metastatic cancer cells." (PMID 31370904, 2019).
monocytopenia (1 paper, 2024). "Thus, dysregulation of the TYROBP/DAP12 pathway may be involved in the monocytopenia and increased inflammatory cell death observed in VEXAS patients." (PMID 38291039, 2024).
multiple myeloma (1 paper, 2024). "To further analyze how TYROBP affected MM progression, we verified the low expression of TYROBP in multiple myeloma bone marrow samples and in vitro cell adhesion assay found that the high expression of TYROBP promoted cell adhesion." (PMID 38549127, 2024). "To further explore the possible molecular function of TYROBP gene within multiple myeloma, we carried out GSEA on genes of high- and low-TYROBP-expression groups." (PMID 38549127, 2024).
myeloma (1 paper, 2024). "As revealed by Western-blotting assays and PCR, TYROBP expression successfully increased in myeloma cells." (PMID 38549127, 2024). "Transwell migration assay suggested that the migration of myeloma cells was reduced when TYROBP was highly expressed." (PMID 38549127, 2024). "Therefore, we investigated how TYROBP affected myeloma cell adhesion and migration when TYROBP was highly expressed in MM cells." (PMID 38549127, 2024).
non-small cell lung carcinoma (1 paper, 2021). A group of at least three distinct histological types of lung cancer, including non-small cell squamous cell carcinoma, adenocarcinoma, and large cell carcinoma. "Apart from TYROBP, several candidate biomarkers encode functional Cluster of Differentiation (CD) molecules and contribute to the classification of different immune cells during the initiation and progression of non-small cell lung cancer." (PMID 34575089, 2021).
osteonecrosis (1 paper, 2023). A none disease characterized by death of bone tissue due to a lack of blood supply. "Together, these data suggested that the four key differential genes ASXL1, BNIP3L, FCGR2A and TYROBP were significantly associated with osteonecrosis of the femoral head." (PMID 36631868, 2023). "The results showed that eighteen differential genes were annotated, among which BNIP3L, ASXL1, FCGR2A and TYROBP were highly correlated with osteonecrosis." (PMID 36631868, 2023). "Through animal experiments, it was confirmed that ASXL1, BNIP3L, FCGR2A and TYROBP screened from the comparative analysis of multiple genes in the database were closely related to GIONFH, which is important for early diagnosis of Glucocorticoid-induced osteonecrosis of the femoral head." (PMID 36631868, 2023).
seminoma (1 paper, 2020). A radiosensitive malignant germ cell tumor found in the testis (especially undescended), and extragonadal sites (anterior mediastinum and pineal gland). "The overexpression of TYROBP in seminoma was also observed in our study and had predictive value for poor prognosis in patients with seminoma." (PMID 33104706, 2020). "In addition, the results of a genome-wide cDNA microarray analysis showed that TYROBP was upregulated 5-fold or more in seminoma." (PMID 33104706, 2020). "According to Kaplan–Meier survival analyses, over-expression of TYROBP and CD68 were significantly correlated with poor prognosis in seminoma (P < 0.05)." (PMID 33104706, 2020). "Three novel biomarkers, TYROBP, CD68 and ITGAM, were identified from databases and correlated with poor prognosis in patients with seminoma." (PMID 33104706, 2020). "Ultimately, TYROBP, CD68, and ITGAM were considered three prognostic biomarkers in seminoma." (PMID 33104706, 2020). "In conclusion, our study demonstrated that TYROBP, CD68, and ITGAM could be regarded as prognostic biomarkers and therapeutic targets for seminoma patients." (PMID 33104706, 2020).
tenosynovial giant cell tumour (1 paper, 2023). "MMP9, SPP1, and TYROBP were identified as osteoclast-specific up-regulated genes of the tenosynovial giant cell tumour via bioinformatic analysis, which had a reasonable diagnostic efficiency and served as potential drug targets." (PMID 38017559, 2023).
tumor (96 papers, 2007 to 2025). "Patients identified as high-risk, characterized by markers such as FCER1G and TYROBP, display “cold tumor” phenotypes, typified by low infiltration of CD8 T cells and elevated levels of PD-L1-expressing macrophages." (PMID 40438577, 2025). "In our present study, TYROBP overexpression was associated with tumor stage and poor survival of GC patients." (PMID 38817876, 2024). "Among them, Module2 (highly express RNASE1, C1QA, CD163, CD14, C1QC, FCGRT, and MS4A7) and Module10 (highly express APOC1, CTSB, CTSL, and TYROBP) are more likely to display the characteristics of tumor-associated macrophages (TAMs)." (PMID 35990663, 2022). "TYROBP expression was significantly associated with the tumor grade, and increased with advanced grade (p < 0.001)." (PMID 34162355, 2021). "This is consistent with a previous study that found a positive association between TYROBP with macrophage M2, as well as the immunosuppressive and pro-tumorigenic subtype of macrophage in the tumor microenvironment." (PMID 33014868, 2020). "In our study, we found that cell adhesion molecules, chemokine signaling pathway, and neutrophil extracellular trap were mainly enriched by GSEA enrichment analysis on high- and low-TYROBP-expression groups, which were closely associated with tumor migration and invasion." (PMID 38549127, 2024). "Extensive research has indicated a strong association between TYROBP and tumor progression." (PMID 38971817, 2024). "In addition, enrichment analyses were carried out to obtain the TYROBP-associated pathways, and the association of TYROBP with the tumor immune microenvironment was evaluated." (PMID 36181123, 2022). "This is consistent with a previous studies indicating that TYROBP is positively linked with M2 macrophages, and may play an important role in immunosuppression and differentiation of TAMs into M2 macrophages in the tumor microenvironment." (PMID 34926275, 2021). "As mentioned in the preface, a number of studies have also proved that TYROBP is a prognostic marker of tumors and affects tumor progression." (PMID 38549127, 2024). "Among these genes, SPINT2, LNX1, FOXA2, and SOSTDC1 were reported to be related to tumor progression, whereas TYROBP, TREM2, IL23R, CSF2RB, TRAF1, and TGFBR1 were closely associated with immune response." (PMID 36611170, 2023). "TYROBP is involved in the interaction between tumor cells and macrophage M2 to enhance TGF-β secretion in vitro." (PMID 36778919, 2023). "In TME (Tumour Micro Environment), the role of TYROBP and SIRPG in regulating NK cells, leukocyte adhesion, and modulating immune cells is well established." (PMID 37091785, 2023). "We also found that several genes, including TYROBP, CD1C, KIR2DL3, CD3G, and TARP, were significantly highly expressed in patients with a high tumor mutational burden." (PMID 35204406, 2022). "We found that compared with normal kidney tissue, the expression of TYROBP in tumor tissues of ccRCC patients was significantly upregulated." (PMID 36595751, 2022). "Patients in different groups of age, gender, and metastasis shared similar TYROBP mRNA expression levels (all P > .05), while leg/foot exhibited the highest TYROBP mRNA expression compared with other primary tumor sites with a statistical difference (P < .01)." (PMID 36181123, 2022). "Cox regression analysis showed that TYROBP was an independent prognostic factor for predicting OS (P = .005), especially in patients of the male sex, age <18 years, metastasis, and tumor site leg/foot (all P < .05)." (PMID 36181123, 2022). "In the TCGA dataset, the expression levels of CD2, HAVCR2, HLA-C, HLA-DRA, HLA-E, KLRK1, and TYROBP were all significantly downregulated in tumor tissues compared with para-tumor tissues." (PMID 35794593, 2022). "Specifically, SLS-dominant tumors were enriched with M2-like macrophages with high expression of TREM2 and TYROBP, a receptor complex on macrophages recently shown to suppress T-cell function in tumor microenvironment." (PMID 36028490, 2022).
tumor (continued). "Patients in the high TYROBP expression group manifested a higher proportion of leg/foot primary tumor sites than those in the low TYROBP expression group (P < .05)." (PMID 36181123, 2022). "Integrative analysis of single-cell data and spatial transcriptomic profiling of these tumors further revealed a modulatory axis from SLS tumor cells to suppressive TREM2+/TYROBP+ macrophages, leading to T-cell dysfunction." (PMID 36028490, 2022). "The literature reports that TYROBP, TLR4, and ITGAM are involved in the BP to activate macrophages that have been reported as tumor-associated and as the main component of the immune environment in OS35–37." (PMID 34588497, 2021). "For validation, qRT-PCR of an ESCC patient cDNA microarray was performed, and demonstrated that C1QA, C3AR1, LCP2, SPI1, and TYROBP were up-regulated in tumor samples and predict poor prognosis." (PMID 34926275, 2021). "Gene set enrichment analysis (GSEA) based on The Cancer Genome Atlas (TCGA) indicated that TYROBP likely promotes LGG progression by regulating the tumor microenvironment." (PMID 34162355, 2021). "The TIMER2.0 database was used to determine the correlation between TYROBP expression and tumor immune infiltrating cells in the LGG patients." (PMID 34162355, 2021). "TYROBP is primarily enriched in natural killer cell-mediated cytotoxicity and osteoclast differentiation, which would lead to tumor cell apoptosis and promote osteoclast differentiation to cause bone resorption around the tumor." (PMID 34588497, 2021). "Previous studies have shown that TYROBP, also known as DAP12, is overexpressed and related to tumor progression in multiple cancers." (PMID 33014868, 2020). "The ALOX5AP inhibitor zileuton has been shown to decrease tumor-associated macrophage (TAM) infiltration in murine models, while targeting TREM2 and TYROBP may reverse immunosuppression." (PMID 40438577, 2025). "Second, we focused on the role of TYROBP-positive ECs in tumor progression, but other EC clusters may also play important roles in the TME." (PMID 37207157, 2023). "Therefore, we furtherly identified the conserved TYROBP co-expressed network across multiple cancer types to explore its classic function in tumor progression." (PMID 35078433, 2022). "Additionally, the analysis showed that C1QA, C3AR1, LCP2, SPI1, and TYROBP were up-regulated in tumours with the worst prognosis." (PMID 35743646, 2022). "The higher expression of TYROBP was, the more severe the tumor stage was (P < .05)." (PMID 36595751, 2022). "TYROBP was an independent prognostic factor for OS in patients of male sex (HR = 0.528, P = .016), age below 18 years (HR = 0.647, P = .012), metastasis (HR = 0.566, P = .043), and tumor site at leg/foot (HR = 0.585, P = .002)." (PMID 36181123, 2022). "Nevertheless, we established TYROBP overexpression as an independent factor of poor prognosis in LGG, which provides new insights into the pathological mechanisms underlying LGG progression, especially in the context of the tumor immunological environment." (PMID 34162355, 2021). "In May 2020, another study revealed that TYROBP was found to be one of the most significant biomarkers reflecting the immune status of tumor microenvironments and contributing to the distinction of functional and dysfunctional immune cells." (PMID 34575089, 2021). "TYROBP (transmembrane immune signaling adapter TYROBP), which was the second highest interconnected node in the PPI network revealed to be negatively associated with OS, was found to be upregulated in EC tumor tissues." (PMID 34763648, 2021). "In early 2004, TYROBP was shown to be differentially expressed in tumor tissues in contrast in normal tissues, indicating that the gene may help distinguish tumor cells from normal cells." (PMID 34575089, 2021). "Taken together, elevated TYROBP in LGG may lead to poor prognosis by increasing immune cell infiltration in the tumor microenvironment through the activation of these pathways." (PMID 34162355, 2021).
tumor (continued). "TYROBP probably promotes tumor progression by interacting with immune cells." (PMID 33015999, 2020). "In addition, 75% (12 out of 16) of the patients with detectable tumor cells in their blood harvested TYROBP-positive CTCs." (PMID 31370904, 2019). "Moreover, our results revealed a positive correlation between TYROBP and tumor stage in GC." (PMID 38817876, 2024). "Besides, TYROBP is related to the immune infiltration of various immune cells, such as neutrophils, monocytes, and macrophages, and is involved in the regulation of the tumor microenvironment." (PMID 40626122, 2024). "Next, protein tyrosine kinase-binding protein (TYROBP) combined with killer-cell activating receptor-associated protein (KARAP) to form an adapter that is involved in a broad range of biological functions, such as anti-viral and anti-tumor activities, and displayed inflammatory reactions." (PMID 36851954, 2023). "In conclusion, our study identified TYROBP-positive ECs as the initiating cells of differentiation in ECs clusters in OS, and suggested that they may play a crucial role in promoting tumor progression through their interactions with malignant cells and regulating immune cell infiltration in the TME." (PMID 37207157, 2023). "TYROBP may promote tumor progression by interacting with immune cells." (PMID 36595751, 2022). "Besides, TYROBP mRNA expression was significantly associated with the tumor site (P < .01) but had no remarkable relationship with age, gender, and metastasis status (all P > .05)." (PMID 36181123, 2022). "We also identified a conserved interaction between tyrosinase binding protein (TYROBP) present on hybrid cells and CD44 present on tumor cells, in all patients." (PMID 39030653, 2024). "CD53 was highly expressed in both tumor and normal tissues, while FCER1G and TYROBP showed higher expression in tumors compared to normal tissues." (PMID 38971817, 2024). "Tyrosine kinase binding protein (TYROBP), also known as DAP12, is highly expressed in various cancers and is related to tumor progression." (PMID 35185791, 2022). "In this study, using RNA-seq data of 576 HCC patients, a panel of seven genes (including LCP2, TYROBP, ZAP70, PTPRC, FYN, WAS and NCF4) has been identified which are independent predictors of delayed tumor recurrence and improved patient prognosis." (PMID 34834481, 2021). "Our findings provide new insights into the oncogenic role of TYROBP in LGG, especially with regards to the immunological status of the tumor microenvironment." (PMID 34162355, 2021). "TYROBP and C1QB were mainly located in tumor cells, which needed further validation in the experiments." (PMID 33014868, 2020). "CD8A, DOK2, CX3CR1, TYROBP, CXCL9, CD300LF, and IFNG were identified as significant DEGs between tumor samples with high and low CD200R1 expression." (PMID 32635224, 2020). "In addition, the TYROBP-SYK pathway promotes TGF-β secretion in macrophages, while this in term promotes tumor progression." (PMID 38549127, 2024). "TYROBP, also known as DAP12 is notably positive with tumor progression in multiple cancers." (PMID 38817876, 2024). "In addition, the high expression of TYROBP and C1QB were also validated in the GC tumor tissues compared with the adjacent mucosa tissues using the ZJU cohort (PTYROBP = 0.045, PC1QB = 0.031)." (PMID 33014868, 2020). "Non-tumor components included endothelial cells (expressing VWF, CDH5, ECSCR, SLCO2A1, and MYCT1), pericytes (marked by RGS5, MCAM, and PDGFRB), normal oligodendrocytes (showing PTGDS, MBP, TF, and MOG expression), and TAMs (identified by CD14, AIF1, FCER1G, FCGR3A, TYROBP, and CSF1R)." (PMID 41394801, 2025). "Specifically, we observed that TYROBP-positive ECs showed the strongest interaction with malignant cells and may serve as initiating cells by secreting TWEAK and other proteins that influence tumor progression." (PMID 37207157, 2023).
tumor (continued). "Moreover, we demonstrated that TYROBP expression was significantly related to the tumor site, but had no remarkable relationship with age, gender, and metastasis status." (PMID 36181123, 2022). "Thus, TYROBP might be a negative factor in anti-tumor immune response." (PMID 33014868, 2020).